GAMT (guanidinoacetate N-methyltransferase)
Description:
Converts guanidinoacetate to creatine, using S-adenosylmethionine as the methyl donor. Important in nervous system development.
Synonyms: PIG2; TP53I2; CCDS2; HEL-S-20
Tractability: Small molecule: a structure with a bound ligand is known; it has a binding pocket of medium quality. PROTAC: ubiquitination databases record sites on it.
Target class: Enzyme; Transferase
Gene: Protein-coding gene on chromosome 19 (1,397,026 to 1,401,570, reverse strand). Ensembl gene ENSG00000130005.
Pathways (Reactome):
Metabolism: Creatine metabolism
Gene Ontology:
Molecular function: guanidinoacetate N-methyltransferase activity; protein binding; methyltransferase activity
Biological process: creatine biosynthetic process; creatine metabolic process; muscle contraction
Cellular component: cytoplasm; cytosol; nucleus
Genetic constraint (gnomAD): Loss-of-function variants: 26 observed, 23.47 expected, observed/expected ratio (o/e) 1.11, 90% interval 0.81 to 1.54. The synonymous counts are far from expectation, so gnomAD's model fits this gene poorly and the ratio says little. Missense variants: 412 observed, 300.01 expected, observed/expected ratio (o/e) 1.37, 90% interval 1.27 to 1.49. Synonymous variants: 169 observed, 126.63 expected, observed/expected ratio (o/e) 1.33, 90% interval 1.18 to 1.52.
Gene-disease validity (ClinGen):
ClinGen rates the evidence that GAMT causes each of these diseases.
guanidinoacetate methyltransferase deficiency (autosomal recessive): Definitive. A creatine deficiency syndrome characterized by global developmental delay/intellectual disability (DD/ID), prominent speech delay, autistic/hyperactive behavioral disorders, seizures, and various types of pyramidal and/or extra-pyramidal manifestations.
Homologues: Orthologues: dog GAMT (89% identical), mouse Gamt (88% identical), guinea pig GAMT (87% identical), rat Gamt (87% identical), pig GAMT (85% identical), chimpanzee GAMT (83% identical), macaque GAMT (81% identical), tropical clawed frog gamt (72% identical), zebrafish gamt (72% identical).
Diseases named in the same sentence as GAMT in open-access papers:
GAMT is named in the same sentence as 53 diseases in open-access papers, as found by Europe PMC text mining. Sharing a sentence is not in itself a finding about the gene and the disease. The quoted sentences say what the papers report.
creatine deficiency syndromes (13 papers, 2019 to 2025). "Loss-of-function mutations in the genes encoding either of these enzymes (GATM or GAMT, respectively) lead to a disorder referred to as Cerebral Creatine Deficiency Syndrome (CCDS)." (PMID 40338959, 2025). "In our case series, case 3 was diagnosed as having guanidinoacetate methyltransferase (GAMT) deficiency, a rare but treatable subtype of cerebral creatine deficiency syndromes (CCDS)." (PMID 40955218, 2025). "Of clinical relevance is the diagnosis of patients with AGAT deficiency but also the potential role of AGAT as therapeutic target for the treatment of another creatine deficiency syndrome, guanidinoacetate N-methyltransferase (GAMT) deficiency." (PMID 39684202, 2024). "The identification of primary creatine deficiency syndromes (CDS), including GAMT deficiency, has clarified the critical role of Cr metabolism in brain development and function." (PMID 41373441, 2025). "In-born errors of human metabolism can provide natural loss-of-function models, and in the last 30 years, creatine deficiency syndrome (CDS) has been described in patients with AGAT, GAMT and CrT mutations." (PMID 38639724, 2024). "Creatine deficiency syndromes (CDS), caused by mutations in GATM (AGAT), GAMT, and SLC6A8, mainly affect the central nervous system (CNS)." (PMID 38745894, 2024). "Humans with mutations in AGAT, GAMT, or SLC6A8 display cerebral creatine deficiency syndromes (CCDSs), which are rare diseases that are characterized by the disruption of the synthesis or transfer of creatine." (PMID 36732069, 2023). "In 2024, the ClinGen Cerebral Creatine Deficiency Syndromes Variant Curation Expert Panel (CCDS VCEP) established gene-specific variant classification guidelines for all three genes implicated in cerebral creatine deficiency syndromes, including GAMT." (PMID 41373441, 2025).
epilepsy (8 papers, 2014 to 2025). A brain disorder characterized by episodes of abnormally increased neuronal discharge resulting in transient episodes of sensory or motor neurological dysfunction, or psychic dysfunction. "Guanidinoacetate Methyl Transferase (GAMT) deficiency is a rare disease characterized by neurodevelopmental derangements, epilepsy, and movement disorders." (PMID 41373441, 2025). "Epilepsy improves in about two-thirds of the patients with GAMT deficiency and movement disorder improves in about 50% of the patients with GAMT deficiency." (PMID 32752260, 2020). "GAMT (Guanidinoacetate N-Methyltransferase): Cerebral creatine deficiency syndrome 2 (epilepsy, intellectual disability, and altered speech development)." (PMID 31031802, 2019). "Clinically, untreated GAMT deficiency mainly results in expressive language impairments, extrapyramidal movements, epilepsy, autistic and self-injurious behaviour, and developmental delay." (PMID 24422943, 2014). "GAMT defects present with early-onset encephalopathy with severe developmental delay/intellectual disability, epilepsy, and movement disorders." (PMID 34440375, 2021). "Notably, human GAMT deficiency is associated with severe epilepsy that does not improve with creatine-supplementation, but does respond to GA lowering strategies." (PMID 32038270, 2019). "These discrepancies found in the brains of GAMT KO mice, as compared with human CSF, could explain the lack of severe neurological symptoms such as epilepsy and ataxia observed in these mice." (PMID 34440375, 2021).
Intellectual disability (5 papers, 2019 to 2025). "Of note, the case in Fam24 was initially diagnosed as mental retardation and was subsequently corrected as guanidinoacetate methyltransferase deficiency disease after the identification of a recessive mutation in GAMT which was further confirmed by clinical re-examination." (PMID 31852928, 2019). "Behavioral disorders in GAMT-deficient subjects have not been well characterized from a clinical point of view, and are usually associated with severe intellectual disability." (PMID 34440375, 2021).
Cerebral creatine deficiency syndrome 2 (4 papers, 2019 to 2025). "Guanidinoacetate methyltransferase deficiency (GAMT-D) is one of three cerebral creatine (Cr) deficiency syndromes due to pathogenic variants in the GAMT gene (19p13.3)." (PMID 34440375, 2021).
Behavioral disorders (3 papers, 2021 to 2024). "Behavioral disorder is frequently associated with GAMT deficiency, mainly consisting of autistic features, hyperactivity, and aggressive and self-injurious behavior." (PMID 34440375, 2021).
chronic heart failure (3 papers, 2019 to 2024). "Creatine‐deficient GAMT KO mice have mild impairment of baseline haemodynamics; however, this did not prove to be detrimental in the setting of chronic heart failure." (PMID 36178450, 2023). "We have shown that aging GAMT–/– hearts have hemodynamic impairment, but without evidence of adverse LV remodeling or congestive heart failure." (PMID 32038270, 2019).
developmental delay (3 papers, 2014 to 2021). "Although cognitive impairment and developmental delay are the hallmarks of human Cr deficiency syndromes, muscular hypotonia and myopathy were also described in patients with AGAT, GAMT, and CT1 deficiency." (PMID 30013483, 2018).
autism (2 papers, 2017 to 2021). Persistent deficits in social interaction and communication and interaction as well as a markedly restricted repertoire of activity and interest as well as repetitive patterns of behavior. "We sequenced GATM, GAMT and SLC6A8 genes in 166 patients with autism (coding sequence, introns and adjacent untranslated regions)." (PMID 28758966, 2017). "In summary, there were no apparent associations of variants in GAMT and SLC6A8 genes with autism." (PMID 28758966, 2017).
Cognitive impairment (2 papers, 2018 to 2021). Abnormal cognition is characterized by deficits in thinking, reasoning, or remembering. "While subtle cognitive impairment cannot be ruled out on the basis of present data, the severe intellectual impairment observed in children with GAMT defects is certainly not part of the GAMT KO mouse phenotype." (PMID 34440375, 2021).
gastric cancer (2 papers, 2022 to 2024). A primary or metastatic malignant neoplasm involving the stomach. "The four nucleotide metabolism-related genes that make up NMRI (GAMT, ORC1, CNGB3, and SERPINE1) were verified in an external dataset and are a valid predictor of prognosis for patients with gastric cancer." (PMID 38880869, 2024). "The expression of GAMT was considerably down-regulated in gastric cancer tissues when compared to normal gastric tissues, while the expression of ORC1, CNGB3, and SERPINE1 was significantly up-regulated in gastric cancer tissues." (PMID 38880869, 2024).
homocystinuria (2 papers, 2015 to 2019). An autosomal recessive inherited metabolic disorder caused by mutations in the CBS, MTHFR, MTR, and MTRR genes. "As we have also found 5 patients besides classical homocystinuria, two with MPS, two patients with GAMT deficiency and one with sitosterolemia." (PMID 31379716, 2019).
argininosuccinic aciduria (1 paper, 2018). "In our set of 46 IEMs tested, four diagnoses remained undetected by the standard NGMS workflow: guanidinoacetate methyltransferase (GAMT) deficiency, argininosuccinic aciduria, dimethylglycine dehydrogenase deficiency, and lysinuric protein intolerance." (PMID 29453510, 2018).
asthma (1 paper, 2022). "We found that GATM was significantly expressed in the mouse asthma model, but not GAMT and slc6a8." (PMID 36177049, 2022).
Ataxia (1 paper, 2020). Ataxia refers to impaired coordination of voluntary muscle movement. "In a study, 50% of the patients who were older than 6 years of age at the time of the diagnosis of GAMT deficiency presented with ataxia." (PMID 32752260, 2020). "GAMT deficiency leads to complex movement disorders in combination with ataxia and tremor; choreoathetosis and dystonia; dystonia, chorea, and ataxia; myoclonus and bradykinesia; or ballismus and dystonia." (PMID 32752260, 2020).
colitis (1 paper, 2021). Inflammation of the colon. "Additionally, underexpression of GAMT (rate-limiting step of Cr biosynthesis) can be linked to a colitis phenotype, among other conditions, although CrM administration in homozygous GAMT mutants may ameliorate the symptoms." (PMID 33918657, 2021).
creatine synthesis disorder (1 paper, 2025). "Guanidinoacetate methyltransferase (GAMT) deficiency is a creatine synthesis disorder caused by biallelic pathogenic variants in GAMT." (PMID 40330029, 2025).
Failure to thrive (1 paper, 2018). Failure to thrive (FTT) refers to a child whose physical growth is substantially below the norm. "L-Arginine:glycine amidinotransferase and GAMT deficiency in transgenic mice leads to Cr-dependent failure to thrive with reduced body weight and length." (PMID 30013483, 2018).
glioblastoma (1 paper, 2024). The most malignant astrocytic tumor (WHO grade IV). "Inhibiting enzymes AGAT or GAMT will slow down the creation of creatine, potentially improving the prognosis of those with glioblastoma." (PMID 39247004, 2024).
melanoma (1 paper, 2017). A malignant, usually aggressive tumor composed of atypical, neoplastic melanocytes. "The higher mRNA expression levels of GAMT in the three tumorigenic cell lines in comparison to GAMT levels observed in Melan-a cells confirmed alterations in the synthetic biochemical pathway of this metabolite in melanoma cells." (PMID 28198377, 2017).
neuroblastoma (1 paper, 2012). Neuroblastoma (NB) is the most common solid, extracranial childhood tumor. "Previous studies demonstrated GAMT activity in neuroblastoma cell lines." (PMID 22536786, 2012).
Sepsis (1 paper, 2017). Sepsis is defined as life-threatening organ dysfunction caused by a dysregulated host response to infection. "As apoptosis induces immunosuppression, the reduced expression of the anti-apoptotic genes (IGF1, GAMT) may have a role in the immune suppression phase of sepsis and support the concept of LPS induced immune regulation/paralysis." (PMID 28056766, 2017).
Stroke (1 paper, 2019). Sudden impairment of blood flow to a part of the brain due to occlusion or rupture of an artery to the brain. "Instead, we propose that reduced stroke work in GAMT–/– mice represents a compensatory adaptation to reduce energy requirements, and calculate that the GAMT–/– heart requires 33% less energy from ATP to perform their external work." (PMID 32038270, 2019).
urea cycle disorder (1 paper, 2021). A genetic inborn error of metabolism characterized by the deficiency of one of the enzymes necessary for the urea cycle. "Ornithine, whose levels negatively correlate with GAA in patients with GAMT deficiency did not corelate with either GAA or creatine levels in patients with urea cycle disorders." (PMID 34471603, 2021).
X-linked creatine transporter deficiency (1 paper, 2025). "These include X-linked creatine transporter deficiency (CTD), guanidinoacetate methyltransferase (GAMT) deficiency, and l-arginine:glycine amidinotransferase (AGAT) deficiency." (PMID 40078706, 2025).
tumor (6 papers, 2015 to 2025). "On the other hand, various genes were associated with overall survival, such as CLUAP1, which participates in tumor growth and cytoskeleton regulation; and the enzyme GAMT, which converts S-adenosylmethionine to creatine in order to foster high energy demands." (PMID 31142279, 2019). "GAMT expression is low in PC cells, and might act as a tumor suppressor." (PMID 38297362, 2024). "WB of the harvested tumor tissues showed that circCGNL1 overexpression significantly inhibited HDAC4 phosphorylation and RUNX2 expression but promoted GAMT expression." (PMID 38297362, 2024).
movement disorder (5 papers, 2015 to 2025). Neurological conditions resulting in abnormal voluntary or involuntary movement, which may impact the speed, fluency, quality and ease of movement. "Two hypotheses could be proposed to explain the association of a low Cr/GAA ratio with a partial deficit of GAMT activity and a clinical picture characterized by the presence of mixed movement disorders." (PMID 25874057, 2015). "Physiological Cr levels are important for psychomotor development, and reduced Cr in GAMT-D causes biochemical alterations in the skeletal muscle; therefore, several studies have explored movement disorders in GAMT-KO mice." (PMID 41373441, 2025). "Guanidinoacetate (GAA) methyltransferase (GAMT, EC 2.1.1.2) deficiency (MIM 601240) is a severe inherited disorder of Cr synthesis that results in postnatal neurodevelopmental impairment, developmental and epileptic encephalopathy and movement disorders." (PMID 41373441, 2025). "For this reason, several studies have explored movement disorders in GAMT KO mice." (PMID 34440375, 2021).
metabolic disorders (4 papers, 2023 to 2025). "Their classification of GAMT deficiency as one of the rare metabolic disorders with significant treatment promise if detected early was supported by our study, in which MRI, MRS, and genetic confirmation were used to establish the diagnosis." (PMID 40955218, 2025). "Genetic variants in the GAMT gene cause CCDS2, an autosomal recessive inherited metabolic disorder." (PMID 40217354, 2024).
cancer (2 papers, 2023 to 2024). A tumor composed of atypical neoplastic, often pleomorphic cells that invade other tissues. "AMPK can induce caspase-family members, leading to cancer cell apoptosis, although the corresponding mechanism of GAMT in PC cell apoptosis remains unclear." (PMID 38297362, 2024). "Currently, studies on regulation of GAMT in cancer are still scarce." (PMID 38297362, 2024).
myopathy (2 papers, 2018 to 2020). A disease of the muscle in which the muscle fibers do not function properly. "Balestrino and Adriano suggest that guanidinoacetate might explain the difference between AGAT- and GAMT-deficient mice in simvastatin-induced myopathy." (PMID 32594255, 2020). "Therefore, (phospo) guanidinoacetate cannot completely explain the milder phenotype of GAMT-deficient mice, but we agree that it might contribute to ameliorate statin-induced myopathy in GAMT-deficient mice compared with AGAT-deficient mice." (PMID 32594255, 2020).
infection (1 paper, 2020). The state of being infected such as from the introduction of a foreign agent such as serum, vaccine, antigenic substance or organism. "With regard to creatine metabolism, expression of creatine synthesis enzyme genes GATM and GAMT decreased as a result of Mtb infection, while the creatine transporter SLC6A8 and creatine kinase (brain-type, CKB) were increased, most notably in our M2 infection model." (PMID 32341411, 2020).
GAMT also shares sentences with these, for which no sentence is quoted: breast carcinoma (2 papers); Bardet-Biedl syndrome (1); Childhood onset (1); congenital nephrotic syndrome (1); deficiencies (1); Duchenne muscular dystrophy (1); Dystonia (1); galactosemia (1); glycine encephalopathy (1); infantile bilateral striatal necrosis (1); juvenile Huntington’s chorea (1); Leigh syndrome (1); lymphoma (1); lysinuric protein intolerance (1); methylmalonic acidemia (1); Mucolipidosis IV (1); mucopolysaccharidoses (1); Neurodevelopmental delay (1); pancreatic cancer (1); pyridoxine-dependent epilepsy (1); Seizure (1); sitosterolemia (1); Wilson disease (1).